CASP8 (caspase 8)
Diseases named in the same sentence as CASP8 in open-access papers (continued):
Sharing a sentence is not in itself a finding about the gene and the disease.
infection (continued). "The failure of Casp8/Ripk3/Casp1/11−/− BMDMs to restrict B. thailandensis intercellular spread via cell-cell fusion and intracellular replication suggested that Casp8/Ripk3/Casp1/11−/− mice would be highly susceptible to severe lethal infection." (PMID 34154417, 2021). "Because B. thailandensisvgrG5ΔCTD was not efficiently cleared from Casp8/Ripk3/Casp1/11−/− BMDMs, we hypothesized that Casp8/Ripk3/Casp1/11−/− mice may be more susceptible to infection than WT mice." (PMID 34154417, 2021). "Therefore, GSDMD and multiple caspases (CASP1, CASP7 and CASP8) operate downstream of the NAIP5/NLRC4 inflammasome for restriction of infection by pathogenic bacteria." (PMID 31251782, 2019). "Furthermore, our data demonstrated that caspase-8 was activated during the infection and caused the activation of Bid." (PMID 29184851, 2017). "Ripk3-/-Casp8-/- mice also had equivalent levels of cytokine responses in the lung, similar viral burdens, and similar kinetics of weight loss over the course of the infection." (PMID 27737018, 2016). "Similarly, individuals with mutations in the adaptor FADD suffer from recurrent infections and liver pathology, suggesting a role for caspase-8 and FADD in antimicrobial responses." (PMID 27737018, 2016). "Similarly, mice in which Caspase-8-mediated apoptosis is impaired (by a Caspase-8 mutation that renders Caspase-8 unable to auto-process and does not engage apoptosis but remains able to inhibit necroptosis) can also overcome infection with IAV." (PMID 36240069, 2022). "Therefore, identification of ZBP1-regulated TRIFosome formation, CASP8 activation, and IL-1β production provides novel points of regulation that could be relevant in the context of various pathogenic infections." (PMID 33397971, 2021). "Given our observation that PANoptosis-deficient BMDMs (Casp8/Ripk3/Casp1/11−/−) displayed distinct cell death activation kinetics during B. thailandensis infection, we biochemically examined the activation of pyroptotic, apoptotic, and necroptotic pathways at 24 h of infection." (PMID 34154417, 2021). "Additionally, Casp8/Ripk3/Casp1/11−/− mice, which are deficient in PANoptosis, allow the study of the combined roles of pyroptosis, caspase-8-dependent apoptosis, and necroptosis during infection." (PMID 34154417, 2021). "In contrast to wild-type CDV strains, infection of Vero cells with CDV Ond causes caspase-3- and caspase-8-mediated apoptosis." (PMID 41405202, 2026). "In certain infections (e.g., Salmonella), caspase-1 and -8 can be independently activated, with caspase-8 activation being dependent on NLRC4 and ASC." (PMID 41208996, 2025). "The expressions of Ccl7, Ccl9, Cd74, and Casp8 were highest in uninfected samples but decreased on the first day of infection and then gradually increased." (PMID 40170749, 2025). "Western blot analysis of infected whole lung tissue confirmed that N4BP1 was cleaved during infection, and this cleavage was dependent on caspase-8 and TNF." (PMID 41233351, 2025). "We observed that caspase-8 was inhibited throughout the infection, and the necroptosis pathway was also suppressed due to the inhibition of phosphorylation and activation of RIPK1, RIPK3, and MLKL, mediated by the TNFα and NF-κB signaling pathways." (PMID 40607949, 2025). "By contrast, a time course of caspase-8 activation in ΔospC1-infected cells showed that cleaved caspase-8 began to accumulate at 6 h post-infection (Fig. EV2F)." (PMID 40931196, 2025). "Caspase-8 is known to play a pivotal role in regulating host cell death following pathogen infection." (PMID 40607949, 2025). "Studies have shown that LPS infection enhanced the expression of Caspase-3, Caspase-8, Caspase-9, and BAX genes and proteins while reducing the levels of BCL-2 gene expression and protein abundance." (PMID 40136393, 2025).
infection (continued). "During mono - infection (with A. salmonicida or GCRV-I) and coinfection, gcHnf4α overexpression consistently increased aif, caspase 3 and caspase 9 mRNA levels, with caspase 8 expression induced only during single-pathogen infections." (PMID 40920830, 2025). "Our analysis revealed significant upregulation of key apoptosis-related genes, including caspase-7 (P = 0.022), caspase-8 (P = 0.0003), and caspase-9 (P = 0.0003), in response to infection." (PMID 41048496, 2025). "For example, porcine epidemic diarrhea virus (PEDV) triggers the induction of SGs early in infection but triggers cleavage of G3BP1 via caspase 8 to inhibit their formation late in infection." (PMID 40145738, 2025). "Enzymatic activity assays mirrored these trends: caspase 3/9 activities were significantly elevated in all infection models, whereas caspase 8 activity remained unaltered." (PMID 40920830, 2025). "The relative contributions of caspase-6 and caspase-8 to cell death during WT EMCV infection will be a subject for future work." (PMID 39928567, 2025). "Our study demonstrates a critical role for Casp8 in preventing infection and inflammation-induced Ripk3-mediated necroptosis in HSPCs." (PMID 38637559, 2024). "Caspase-8 is one of the most universal caspases, playing an important role in regulating infection and inflammation, and is involved not only in apoptosis but also in pyroptosis." (PMID 39595247, 2024). "In this study, inhibition of caspase-8 restored secretion of IL-18 in infections with hyper-virulent GAS, while inhibition of caspase-3 did not." (PMID 38408992, 2024). "Specifically, in the death receptor-mediated apoptosis signaling pathway, downregulation of TNFα, TRAIL, CASP6, and CASP8 was observed, while several genes in the autophagy and mitophagy pathways showed upregulated expression post-infection." (PMID 39650642, 2024). "In this study, we cultured bone-derived chicken dendritic cells (ck-BM-DC) and examined gene expression levels of IFN-α, TLR-3, TLR-7, MHC-I, IL-1β, IL-6, Mx, Casp-3, and Casp-8 pre/post infection with AIV." (PMID 39281683, 2024). "For example, cleavage of caspase-3 (VACV, Modified Vaccinia Ankara, MVA) and caspase-8 (MVA) has been detected at late stages of infection." (PMID 39093901, 2024). "Necroptosis is unleashed as an alternative to extrinsic apoptosis when caspase-8 activity is compromised, a common occurrence during infection with DNA viruses that deploy specific cell death suppressors such as CMV vICA." (PMID 39772130, 2024). "Apoptosis acts as an important defense mechanism of host against infection, in which caspase 8, caspase 3, Bcl-2 and Bax play key roles." (PMID 38439110, 2024). "Since caspase-8 inhibition restored the secretion of IL-8 and IL-18 in response to 5448AP infections, its intracellular abundance was assessed in moDCs." (PMID 38408992, 2024). "Inhibition of host initiator caspase-8 restored the secretion of both cytokines in response to infections." (PMID 38408992, 2024). "Such mice developed BM failure upon infection or low dose polyI:C/LPS injections due to the hypersensitivity of Casp8−/− HSPCs to infection or inflammation-induced necroptosis which can be prevented by Ripk3 deletion." (PMID 38637559, 2024). "While both can occur during an infection, AIV proteins have been shown to block the Caspase-3 (Casp-3) and Caspase-8 (Casp-8) activation causing a shift from the apoptotic pathway to the necrotic pathway." (PMID 39281683, 2024). "Luminescence-based measurement over a period of 8 h revealed a stable increase of caspase-8 activity in response to 5448AP infections In contrast, 5448 infections rather suppressed caspase-8 activity." (PMID 38408992, 2024). "For instance, it was shown that both Casp1/11–/– and Casp8–/–Ripk3–/– mice resisted an intravenous Salmonella Typhimurium infection, while Casp8–/–Ripk3–/–Casp1/11–/– mice succumbed to this infection." (PMID 37080966, 2023).
infection (continued). "Influenza A virus (IAV) infection of cells caused GSDME activation, cytokine release, and cell death, in a PKR-dependent but NLRP1-independent manner, involving caspase-8 and caspase-3." (PMID 37680489, 2023). "We found only mitochondrial-mediated apoptotic mutant MCMV (∆M38.5/41.1) infection was able to increase caspase-3/7 and caspase-8 activity." (PMID 37012234, 2023). "In contrast, Casp8+/-Ripk3–/–Casp1/11–/– mice disabled for necroptosis and pyroptosis cleared the infection with normal kinetics, in line with the ability of Gsdmd–/–Mlkl–/– mice to clear intestinal C. rodentium loads." (PMID 37080966, 2023). "Quantitative analysis of protein levels performed by dot blot scanning showed that the expression levels of ACE-2, annexin-V, flotillin-1, TLR-7, LAMP, TNF-α, caspase-1, caspase-8, and others were altered in EVs after infection." (PMID 36979955, 2023). "Together, these data indicate that infection with Mm induces necrosis in BMDMs, and that imatinib limits necrosis in a manner that depends upon CASP8." (PMID 37200402, 2023). "Meanwhile, our research provides a reference dataset for in-depth studies on the molecular mechanisms of (TLR1-2) - MyD88 - FADD - Caspase 8 mediating apoptosis pathway in bony fish after the bacterial pathogen infection." (PMID 37056759, 2023). "Among critical inflammation and immune response biomarkers, HSP100, TNF-α, TGIF-1, TGIF-2, mCCL22, iNOS, caspase-1, and caspase-8 were significant at different time points in the infection-derived EVs during CCoV infection of CRFK cells." (PMID 36979955, 2023). "We then sought to dissect which downstream pathways are engaged by caspase-8 in TNF-primed BMDMs to mediate cell death following infection." (PMID 37279255, 2023). "Although both cohorts displayed similar weight changes, Casp8–/–Ripk3–/– mice continued shedding pathogens in their feces until 35 dpi, one week after their Casp8+/-Ripk3–/– littermates had already cleared the infection." (PMID 37080966, 2023). "Using a fluorogenic IETD-AFC assay, we found that infection of MEFs with 10 multiplicity of infection (m.o.i.)of HSV-1 gradually increased caspase-8 activity in total cellular extracts up to 24 h post infection (h.p.i.)after which the activity declined." (PMID 36418547, 2023). "We next gavaged Casp8+/-Ripk3–/– and Casp8–/–Ripk3–/– cohorts with C. rodentium to evaluate the role of caspase-8 during an in vivo infection." (PMID 37080966, 2023). "Fluorescence microscopy has shown the colocalization of caspase-8 and ASC in both pyroptosis-deficient and pyroptosis-sufficient cells in response to infections." (PMID 35563804, 2022). "The infection of lung cells activates caspase-8 to trigger cell death pathways, where apoptosis, pyroptosis, and necroptosis are involved." (PMID 35422702, 2022). "Inhibition of Caspase-8 activity, pharmacologically or upon infection by certain pathogens, therefore promotes TNFR1-induced necroptosis." (PMID 36240069, 2022). "Equal Mlkl expression levels during infection observed in control and Casp8ΔIEC mice highlights the role of Caspase-8 as central cell death regulator to prevent massive and harmful necroptosis." (PMID 34497340, 2022). "In summary, we suggest that caspase-8 plays an important role in cell death induced during B.abortus infection, contributing to inflammation and infection control in mice." (PMID 36532444, 2022). "Our results revealed that the expression of cleaved caspase-8 was detected in THP-1 macrophages upon EV-A71 infection." (PMID 36503883, 2022). "DTMUV infection triggers typical lesions of apoptosis, and caspase-8 and caspase-9 are involved in DTMUV-induced apoptosis." (PMID 35799206, 2022). "Marked CASP8 upregulation has also previously been detected in head-kidney and spleen leukocytes of Totoaba macdonaldi at 24 h post-infection with Vibrio parahaemolyticus and Aeromonas veronii." (PMID 33882827, 2021).
infection (continued). "MRNA levels of CASP3, CASP7, and CASP8 were significantly up-regulated compared to control (p < 0.05) at 6, 12, 24, and 48 h post-infection." (PMID 34451461, 2021). "Here, we found that MO infection-induced activation of caspase-8-dependent apoptosis in cultured MH-S cells, which is similar to the finding in a previous study showing MO-induced caspase-8-dependent apoptosis in sheep airway epithelial cells." (PMID 34678131, 2021). "Similar to Mel-HO cells caspase-8 was activated in MeWo cells after infection with AdV-TRAIL due to leaky expression of TRAIL in the uninduced state and more prominently after full induction of TRAIL expression by Dox." (PMID 34028599, 2021). "Consistent with mouse survival during infection, WT and Gsdmd−/− mice harbored less B. thailandensis, while Casp1/11−/− and Casp8/Ripk3/Casp1/11−/− mice harbored increased bacteria." (PMID 34154417, 2021). "Casp8/Ripk3−/− mice can then be used to study the combined role of the apoptotic and necroptotic pathways during infection with B. thailandensis." (PMID 34154417, 2021). "Infection with ∆M36 resulted in the expected appearance of cleavage-activated CASP8 (~43 and 18 kDa), CASP7 (17 kDa), and CASP3 (17 kDa) cleavage products." (PMID 34578288, 2021). "This review provides the most updated information that caspase 8 skews the NLRP3 inflammasome activation in PANoptosis during pathogen infection." (PMID 34768828, 2021). "Caspase-8 ubiquitination was elevated at K169 in both WT and cKO early post-infection, but was sustained through the late timepoint only in ATG16L1-deficient BMDMs." (PMID 34085925, 2021). "We also detected increased cleavage of caspase-8 and caspase-3 in vivo upon infection of OTUB1FL mice with Lm and treatment with DGal/TNF, respectively." (PMID 33712742, 2021). "While Casp8/Ripk3/Casp1/11−/− BMDMs were protected from cell death in the early stage of infection with B. thailandensis, this delay in cell death resulted in increased formation of MNGCs via cell-cell fusion." (PMID 34154417, 2021). "By suppressing CASP8, vICA blocks both death-dependent as well as death-independent inflammation that appear to be unleashed during ∆M36 infection." (PMID 34578288, 2021). "During infection, NleB1G255S inhibited caspase-8 cleavage in response to FasL stimulation and complemented EPEC ΔnleB1 similarly to NleB1." (PMID 34133469, 2021). "In this study, we found that caspase-3, caspase-8 and caspase-9 activity was significantly higher in the infection groups than in the mock group at 2 h, 4 h, 6 h, and 8 h (P < 0.001), indicating that apoptosis was activated in the infected macrophages." (PMID 32517648, 2020). "Activity of the apoptosis initiator caspase-8 increased post-infection in 65ST and was significantly lower in WT-infected cells." (PMID 33114369, 2020). "Our observations expose that the basal FADD-CASP8 is sufficient to collaborate with the infection-driven elevation in levels of CASP8, cFLIP, and RIPK1 for unleashing extrinsic apoptosis when vICA is absent." (PMID 33126536, 2020). "Casp1–/–;Casp8–/–;Ripk3–/– iBMDMs responded to the infection by upregulation of caspase-11 and underwent cell death, although this killing was less effective with ∼60%–70% of the cells surviving the bacterial assault." (PMID 32735843, 2020).
infection (continued). "An exception was observed for caspase 8 after 2 h infection when M. smegmatis was the strongest inducer." (PMID 31035520, 2019). "Our results suggest that apoptosis mediated by caspase 8 and caspase 3/7 favours M. fortuitum and M. avium intracellular persistence, at least in the early stages of infection." (PMID 31035520, 2019). "A relative increase in the expression of caspase-8 cleavage was observed in M. bovis-infected BMDMs at 6 h post-infection." (PMID 30846986, 2019). "As expected, the results shown that miR-C12 overexpression led to inhibition of caspase 8 mRNA levels by 0.56-fold and 0.39-fold in caspase 8 protein, miR-C12 inhibitor increased caspase 8 mRNA (2.19-fold) and protein levels (1.36-fold) at 24 h post infection." (PMID 31921084, 2019). "Significant increase of intracellular ROS was observed within 60 min of infection when caspases were inhibited by zVAD-fmk, and this effect was further increased with the specific caspase-8 inhibitor zIETD-fmk." (PMID 30154785, 2018). "Caspase 8 can be degraded by autophagy, a pro-survival strategy to counter cellular stress and infection, and, of note, type I IFNs can initiate autophagy." (PMID 30080899, 2018). "A few genes were downregulated 4 h after infection: caspase 8 (Casp8), nuclear receptor subfamily 2, group C, member 2 (Nr2c2/TAK1), mitogen-activated protein kinase 9 (Mapk9/JNK2) and interleukin 6 receptor-alpha (Il6ra)." (PMID 30555476, 2018). "In contrast to naïve animals, N67C infection leads to increased levels of cleaved caspase-3, cleaved caspase-8, cleaved PARP, and granzyme B (GrzB) on days 4 and 6 p.i." (PMID 28874800, 2017). "The expression levels of apoptosis-related proteins were examined by Western Blot; caspase-3, caspase-8, and caspase-9 activation and Bcl-2/Bax levels in A549 cells were assessed following infection with rL-RVG or NDV and treatment with MLA and ACB." (PMID 28974241, 2017). "This only occurs when caspase-8 is blocked, which is relevant to SesT infection as caspase-8 decreases during infection." (PMID 28529959, 2017). "In this study, the expression of caspase-8 was significantly higher in 5b WT-infected PAMs than in 5b ΔAdh-infected PAMs, and the expression of caspase-8 peaked 3 h post-infection (p < 0.05)." (PMID 27046446, 2016). "The cleavage of BID and activation of caspase-9 and -3 were reduced in macrophages pretreated with the caspase-8 specific inhibitor (Z-IETD-FMK) prior to Mtb-infection compared with untreated cells." (PMID 27552917, 2016). "Caspase-8 activates apoptosis in response to infection by pathogens that interfere with NF-κB signaling, including Yersinia, but has also recently been linked to control of inflammatory gene expression." (PMID 27737018, 2016). "Based on our observations that maximal differences between Ripk3-/-Casp8-/- and B6 or Ripk3-/- BMDMs occurred at 6 hours post-infection, we performed RNA-seq analysis on these three genotypes of macrophages 6 hours after LPS stimulation." (PMID 27737018, 2016). "Infection by the bacterial pathogen Yersinia induces innate immune cells to undergo caspase-8-mediated apoptosis, and it has been suggested that apoptosis of bacteria-infected cells promotes immune defense against infection." (PMID 27737018, 2016). "Western blot analysis showed that full-length procaspase-3 decreased in the B.suis.S2 infection group at 24 h post-infection, whereas caspase-9 and caspase-8 increased in the B.suis.S2 infection group at 24 h post-infection." (PMID 26904517, 2016). "Caspase-8 was expressed at much lower levels at the early stages of DENV2 infection in IFI6+/+ cells as compared with vector-high cells, but there was no marked difference at 48 hrs post-infection." (PMID 26244642, 2015). "It has previously been reported that PR cleaves and activates caspase-8 in vitro and during infection." (PMID 26297639, 2015).